SF3B1 (splicing factor 3b subunit 1)
Diseases named in the same sentence as SF3B1 in open-access papers (continued):
Sharing a sentence is not in itself a finding about the gene and the disease.
myeloid neoplasm (48 papers, 2012 to 2026). Proliferation of myeloid cells originating from a primitive stem cell. "Selective XPO1 inhibitors (selinexor, eltanexor) show preferential activity in NPM1-mutated, DEK::NUP214-positive and SF3B1-mutated myeloid neoplasms." (PMID 42071259, 2026). "Mutations in SF3B1 were originally identified in 2011 and are observed across all the spectrum of myeloid malignancies, including MDS, MDS/AML, and AML." (PMID 41464583, 2025). "Mutations in spliceosome genes U2AF1 and SF3B1 have been linked to the expression of oncogenic IRAK4 isoforms in myeloid malignancies." (PMID 38666914, 2024). "It is a myeloid neoplasm with cytopenia and dysplasia characterized by SF3B1 mutation and often ring sideroblasts." (PMID 38835968, 2024). "The 2022 WHO classification of myeloid neoplasms revised the diagnostic criteria for MDS/MPN-RS-T based on SF3B1 mutation and was renamed MDS/MPN-SF3B1-T." (PMID 38714876, 2024). "The 2016 WHO classification of myeloid neoplasms has included SF3B1 mutations among the diagnostic criteria for MDS types with ring sideroblasts." (PMID 36409328, 2023). "The most commonly mutated spliceosome genes in myeloid malignancies, SF3B1, SRSF2, and U2AF1, are also frequently identified in individuals with CHIP." (PMID 38028538, 2023). "An entity of MDS with mutated SF3B1 (MDS-SF3B1) has been included in the two new classifications of myeloid neoplasms recently published: the World Health Organization (WHO) 2022 classification and the International Consensus Classification (ICC) 2022." (PMID 36140729, 2022). "Myeloid neoplasms with SF3B1 and PHF6 double mutations tend to show morphologic evidence of myelodysplasia, increased reticulin fibrosis, an increased blast count, and the risk of leukemia transformation." (PMID 36671709, 2022). "Splicing factor 3b subunit 1 (SF3B1) is one of several genes involved in RNA splicing that is mutated in a variety of myeloid neoplasms." (PMID 36671709, 2022). "It has been reported that an SF3B1 mutation is an early event in myeloid neoplasms, and in MDS/MPN, SF3B1 mutations seem to represent founder mutations followed by secondary hits in genes involved in other signaling pathways, such as JAK2." (PMID 36671709, 2022). "Nevertheless, the findings in this study show that myeloid neoplasms with SF3B1 and PHF6 mutations do occur uncommonly, and seem to be associated with some distinctive features." (PMID 36671709, 2022). "The aim of this study is to report a series of myeloid neoplasms in which concurrent SF3B1 and PHF6 mutations were detected, along with their clinicopathologic and molecular features." (PMID 36671709, 2022). "We report the clinicopathologic and molecular features of 21 myeloid neoplasms with double SF3B1 and PHF6 mutations." (PMID 36671709, 2022). "Recently described SF3B1 mutations appear to be associated with myeloid neoplasms with ring sideroblasts." (PMID 23653870, 2013). "SF3B1 mutations can be detected in other MDS subtypes or other myeloid neoplasms." (PMID 38835968, 2024). "Mutations in the spliceosome genes U2AF1 and SF3B1 have been linked to the expression of oncogenic IRAK4 isoforms in myeloid malignancies, and may impose sensitivity to IRAK4 inhibition." (PMID 38666914, 2024). "Moreover, PHF6 mutations tend to occur late in the course of myeloid neoplasms, either concurrently with or subsequently to SF3B1 mutations in all cases, and are associated with disease progression in a subset of the cases." (PMID 36671709, 2022). "Although the most frequent mutation in MDS/MPN-RS-T is that affecting the SF3B1 gene, the presence of variants in epigenetic genes, such as Bcor, may contribute to the development of this myeloid neoplasm." (PMID 33159179, 2021). "NGS is essential for this diagnosis, as it enables detection of at least one somatic mutation in genes commonly mutated in myeloid neoplasms (e.g., DNMT3A, TET2, ASXL1, SF3B1, SRSF2, etc.)." (PMID 41464583, 2025).
myeloid neoplasm (continued). "In the absence of these three major driver mutations, screening for other mutations associated with myeloid neoplasms, such as ASXL1, EZH2, TET2, IDH1, IDH2, SRSF2, and SF3B1, can help establish the clonal nature of the disease." (PMID 41514563, 2025). "Regarding haematopoietic malignancies, mutations of SF3B1 and SRSF2 are frequently observed in myeloid neoplasms such as myelodysplastic syndrome." (PMID 38918373, 2024). "Our results demonstrated that MDS/MPN is characterized by the presence of mutations commonly identified in myeloid neoplasms, such as TET2, ASXL1, SRSF2, and SF3B1." (PMID 39337700, 2024). "Frequent somatic mutations in splicing factors including SF3B1, SRSF2, and U2AF1 were discovered in myeloid malignancies as well as solid tumors." (PMID 37810965, 2023). "Murine models with conditional heterozygous expression of splicing factor (SF) mutations (SF3B1, U2AF1, SRSF2, ZRSR2) have confirmed the causative effects of RNA splicing dysregulation in the pathogenesis of myeloid malignancies and CLL." (PMID 37463047, 2023). "In myeloid malignancies such as MDS and AML, spliceosome mutations of SF3B1 or U2AF1 lead to formation of hypermorphic IRAK-4 isoforms (IRAK-4-L) which activate myddosomal signaling promoting cell survival." (PMID 37954584, 2023). "Since SF3B1 and PHF6 mutations can both serve as drivers of mutations and play key roles in the development of myeloid neoplasms, it is of clinical importance to clarify this issue." (PMID 36671709, 2022). "Since SF3B1 and PHF6 mutations can both serve as driver mutations and play key roles in the development of a variety of myeloid neoplasms, it is of clinical importance to clarify the issue of their potential mutual exclusivity." (PMID 36671709, 2022). "We summarize that concurrent mutations in SF3B1 and PHF6 are rare, but they do exist in a variety of myeloid neoplasms." (PMID 36671709, 2022). "Subsequently, SF3B1 is the first gene deeply related to a specific morphology in myeloid malignancies." (PMID 36140729, 2022). "Aside from DTA mutations, persons with CH also recurrently carried variants in other genes associated with myeloid neoplasms such as JAK2, SRSF2 and SF3B1." (PMID 36131041, 2022). "In summary, concurrent mutations in the SF3B1 and PHF6 genes are rare in myeloid neoplasms, but they do exist." (PMID 36671709, 2022). "In summary, concurrent mutations in SF3B1 and PHF6 are rare, but they do exist in a variety of myeloid neoplasms, with roles as early initiating events and in disease progression, respectively." (PMID 36671709, 2022). "At the same time, SF3B1 (Splicing Factor 3b Subunit 1), U2AF1 (U2 Small Nuclear RNA Auxiliary Factor 1), NPM1, and FLT3 are rarely mutated in GATA2-mutated myeloid neoplasms." (PMID 35054439, 2021). "In this study, we analyzed the NGS panel test results of 6478 patients to address the question of whether SF3B1 and PHF6 mutations are mutually exclusive in myeloid neoplasms." (PMID 36671709, 2022). "As myeloid neoplasms with PHF6 mutations are rare, the clinical characteristics of patients with these myeloid neoplasms are much less established compared to those of patients with myeloid neoplasms with SF3B1 mutations." (PMID 36671709, 2022).
myeloid neoplasm (continued). "Furthermore, mutations in SRSF2 and SF3B1, which also contained MGO modifications in this study, are observed in 5–75% of patients with various myeloid neoplasms, particularly chronic myelomonocytic leukemia and refractory anaemia with ring sideroblasts." (PMID 35409048, 2022). "It is possible that myeloid neoplasms with SF3B1 and PHF6 double mutations may represent a unique entity among myeloid neoplasms." (PMID 36671709, 2022). "For example, the 7 cases initially diagnosed with HES were split between molecular group 1 (n = 1), group 2 (n = 2) and group 3 (n = 4) and the 9 cases with SF3B1 mutations had been diagnosed with 7 different entities, including HES (n = 2) and 6 WHO-defined subtypes of myeloid neoplasms." (PMID 30573779, 2019). "One possible explanation for myeloid neoplasms with both SF3B1 and PHF6 mutations not having been reported in the literature may be the lack of large-scale studies of myeloid neoplasms that have been assessed for PHF6 mutations." (PMID 36671709, 2022). "In addition to SF3B1, another association between a gene defect and the ring sideroblasts phenotype was defined for PRPF8, for which mutations are reported in approximately 3% of myeloid neoplasms, including MDS, MDS/MPN, and secondary AML." (PMID 36140729, 2022).
acute myeloid leukemia (46 papers, 2013 to 2026). Acute myeloid leukemia (AML) is a group of neoplasms arising from precursor cells committed to the myeloid cell-line differentiation. "In a phenotypical screen of 56 acute myeloid leukemia (AML) patient samples and using a library of 10,000 compounds, we identified a hit with increased sensitivity toward SF3B1-mutated and adverse risk AMLs." (PMID 38517966, 2024). "Ring sideroblasts can also be present in a subset of patients with acute myeloid leukemia (AML), ranging from 5 to 16%, whereas SF3B1 mutations are infrequent." (PMID 36140729, 2022). "Previous studies have demonstrated that the molecular landscape is very different among SF3B1-mutated MDS, MDS/MPN and acute myeloid leukemia patients and that co-mutations contribute to diverse clinical and morphological features." (PMID 38714876, 2024). "Mutations in the splicing factor 3B subunit 1 (SF3B1) gene are the most commonly mutated spliceosome gene, occurring in 25–30% of patients with MDS and 2–5% of patients with acute myeloid leukemia (AML)." (PMID 38997434, 2024). "In acute myeloid leukemia (AML) patients with IDH mutations, frequent mutations in splicing factor mutations are shown including SRSF2 and SF3B1." (PMID 35252202, 2022). "SF3B1 and mutations in it have been exploited extensively as a therapeutic target in FLT3/ITD positive acute myeloid leukemia (AML), endometrial cancer, and hepatocellular carcinoma." (PMID 35230971, 2022). "Recently, a second mutational hotspot has been identified in SF3b1 located in HR9-12 and is associated with acute myeloid leukemias, bladder urothelial carcinomas, and uterine corpus endometrial carcinomas." (PMID 32320410, 2020). "The presence of an SF3B1 mutation appears to be an early event in MDS pathogenesis, being linked to a unique gene expression profile, and is associated with a favorable prognosis and a low risk of progression to acute myeloid leukemia (AML)." (PMID 40729294, 2024). "The outcome of a large study of 533 patients with MDS indicated that patients with SF3B1 mutations were associated with a better overall survival and a lower risk of progression to acute myeloid leukemia compared to patients without SF3B1 mutations." (PMID 33333932, 2020). "Past studies have also shown that inhibition of SF3B1 previously evaluated in the clinic against MDS, acute myeloid leukemia (AML), and chronic monomyelocytic leukemia (CMML) blocks the growth of leukemia cells and exhibits relatively low toxicity toward normal CD34+ hematopoietic progenitors." (PMID 35061527, 2022). "The SRSF2 mutation strongly correlated with old age (P < 0.001), while the mutation status of SF3B1 did not affect overall survival (OS), progression-free survival (PFS), or acute myeloid leukemia (AML) transformation." (PMID 26115659, 2015).
leukemia (43 papers, 2012 to 2025). A malignant (clonal) hematologic disorder, involving hematopoietic stem cells and characterized by the presence of primitive or atypical myeloid or lymphoid cells in the bone marrow and the blood. "It has been suggested that SF3B1 mutations arise later in leukemia development and contribute to disease progression." (PMID 35053445, 2022). "PRPF8 is the only U5 snRNP protein where recurrent somatic mutations have been linked to cancer, joining the ranks of spliceosome factors such as U2AF1 and SF3B1 as frequently mutated in certain types of human cancers, in particular leukemias." (PMID 33584830, 2021). "We identified a novel phosphorylation site created by a SAAV in splicing factor SF3B1, a protein that is frequently mutated in leukaemia." (PMID 29221171, 2017). "In the present study, we report in K562 leukemia cell line that introduction of the hotspot K700E mutation in the gene SF3B1 using CRISPR/Cas9 method results in an increased frequency of multinucleated polyploid giant cells resistant to chemotherapeutic agent and serum starvation stress." (PMID 35478057, 2022). "Besides well-known cases such as BRAF (V600E), KRas (G12D, G13D) or PIK3CA (G118D), we derived previously uncharacterized hotspot mutations such as SF3B1 (K700E) found in eight breast tumors and one leukemia sample." (PMID 31345222, 2019). "Considering that most of the MDS patients with SF3B1 mutation presented a favorable clinical outcome and low risk of progression to leukemia, it may be assumed that SF3B1 gene mutations are less frequent in cases with MDS transformation into AML than in MDS cases." (PMID 36982819, 2023). "Oncogenic mutations in splicing regulators, including SF3B1 and U2AF1, are therapeutic liabilities in leukemias and lymphomas,56." (PMID 38114498, 2023). "Recently, it was suggested that SF3B1, SRSF2, ASXL1, TET2, and DNMT3A gene mutations contribute to the risk of MDS evolution to leukemia and also influence therapy response and overall survival." (PMID 36982819, 2023). "ALKBH5-driven 5ʹ UTR m6A demethylation fine-tunes SF3B1 translation to impacts genome stability and leukemia progression." (PMID 37858219, 2023). "For example, mutations in several protooncogenes, including BRAF (B-Raf serine-threonine kinase), NOTCH1 (Notch 1 receptor) and SF3B1 (splicing factor 3b subunit 1), have been found in hematopoietic progenitor cells isolated from leukemia patients." (PMID 36081905, 2022). "The clonal evolution analysis of FA case (P1001) showed the mutations of UBASH3A, SF3B1, RUNX1 and ASXL1 gradually appeared at the later stage of MDS, while the IDH2 alteration become the dominant clone at the leukemia stage." (PMID 36167633, 2022). "Driven by our observation that SF3B1 inhibition leads to a reduction of R-loops in the genome, we mapped changes in the nascent transcriptome upon SF3B1 inhibition in leukemia." (PMID 35061527, 2022). "The UBASH3A, SF3B1, RUNX1 and ASXL1 mutations gradually appeared and became the major clones at MDS stage, while IDH2 gradually emerged as the dominant clone at leukemia stage." (PMID 36167633, 2022). "Together, our data demonstrate that SF3B1 levels and activity are critical for leukemia cell survival." (PMID 35061527, 2022). "Our present study identifies a previously unidentified regulatory mechanism of the U2 component SF3B1 in pediatric leukemia via USP7 activity and protection against degradation." (PMID 35061527, 2022).
leukemia (continued). "H3B-8800, an orally available small-molecule inhibitor targeting SF3B1, selectively eradicates SF3B1-mutant leukemia cells in xenografts and is currently been investigated in a phase 1/2 clinical trial in AML and MDS." (PMID 35822030, 2021). "In conclusion, SF3B1, SRSF2, ZRSR2 and U2AF1 spliceosomal mutations affect overall and leukemia-free survival in MPN." (PMID 32784800, 2020). "In terms of leukemia-free survival (LFS), the group with SF3B1 mutation had better outcome than unmutated group, HR = 0.63 (95% CI: 0.53–0.75, P < .00001)." (PMID 31124956, 2019). "This patient's leukaemia had another instance of convergent evolution with clonal shifts in relation to prior FCR therapy, where a clone containing a SF3B1 mutation was replaced by another clone harbouring a different SF3B1 mutation." (PMID 27199251, 2016). "For example, human myeloid and leukemia cells engineered to carry heterozygous mutations in both SF3B1 and SRSF2 are not viable." (PMID 40624356, 2025). "We observe that age is highly connected to the mutations SF3B1, SRSF2, and TET2, and the chromosomal abnormality -5/del(5q), which may reflect leukemias deriving from previous MDS clones, resulting as an accumulation of genetic driver events later with age." (PMID 40301336, 2025). "This raises the question of whether this unique state of dysregulation can be exploited to target SF3B1-MT leukemia." (PMID 37463047, 2023). "Although prior studies have reported that mutations in SF3B1, SRSF2, and U2AF1 cause global R-loop augmentation, to our knowledge, no studies thus far have assessed cen-R-loop levels or their roles in the pathogenesis of SF mutant leukemia." (PMID 37463047, 2023). "Our findings suggest that the leukemia cells that depend on high SF3B1 levels might stem from the role of SF3B1 in controlling oncogenic transcription in addition to splicing, leading to its impact on drug resistance in high-risk (HR) cancers." (PMID 35061527, 2022). "Since SF3B1 is often mutated in leukemia cells, we sequenced the SF3B1 gene in MEG-01 cells and confirmed that SF3B1 was not mutated in this cell line." (PMID 26575292, 2015). "Similarly, SF3B1 mutation does not have a poor prognostic effect, yet it is associated with a favorable leukemia-free survival." (PMID 39759649, 2024). "In this study, we report that SF3B1 mutation triggers genomic instability through excessive global and centromeric R-loop accumulation and ATM deletion further exacerbates the dysregulation of this process, ultimately resulting in CIN and possibly contributing to the initiation of leukemias." (PMID 37463047, 2023). "SF3B1 mutations occurring in MDS result in different splicing alterations that define a disease characterized by RS, ineffective erythropoiesis and low risk of conversion to leukemia, and high overall survival (OS), together suggesting a mechanism of action in MDS." (PMID 37007111, 2023). "Mice expressing heterozygous and hematopoietic-restricted SF3B1 K700E mutation do not develop leukemia but exhibit macrocytic anemia due to a block in terminal erythroid maturation, erythroid dysplasia, and long-term hematopoietic stem cell expansion, all of which are characteristic features of MDS." (PMID 35053445, 2022). "We further demonstrate that clinically used SF3B1 inhibitors synergize with CHEK2 inhibitors and chemotherapeutic drugs to block leukemia growth." (PMID 35061527, 2022).